KRT17 (keratin 17)
Diseases named in the same sentence as KRT17 in open-access papers (continued):
Sharing a sentence is not in itself a finding about the gene and the disease.
tumor (continued). "Next, we obtained the total protein expression data for KRT17 in BRCA, LUAD, COAD, UCEC, OV, and KIRC in tumor tissues and normal tissues in the CPTAC dataset, and the total protein expression data for the other cancers were not included in the CPTAC dataset." (PMID 35646078, 2022). "In the present work, we confirmed the close similarities between TB tumor cells and epithelial MC progenitors, evident by expression of GLI1 and its related downstream targets, i.e., KRT17 and SOX9, in both settings." (PMID 32708246, 2020). "Genetic ablation of Krt17 delays tumor development in transgenic mice, suggesting that GLI2-driven KRT17 expression has tumor-promoting activity." (PMID 27512993, 2016). "In this study, we show that KRT17 is invariably induced in OSCC and stimulates the Akt/mTOR pathway and SLC2A1 expression, thereby facilitating tumor growth." (PMID 27512993, 2016). "As expected, KRT8 and KRT17/19 were localized to ovarian surface epithelia of control and TGFBR1-CAAcre mice, with low to undetectable expression in the tumor tissues at the age of 2 months." (PMID 27344183, 2016). "Both H. pylori-exposed gastric epithelial cells and the tumor biopsies demonstrated significant up-regulation of five common genes (IL-8, CLDN1, KRT17, CLDN7 and MMP7) and down-regulation of four common genes (GPER, KIAA1324, ADA and SLC9A2)." (PMID 24321518, 2013). "Furthermore, temporal variation in keratin expression differed between normal and tumor cells, with KRT10 highly expressed exclusively during normal epithelial differentiation, while KRT17 was highly expressed throughout tumor progression." (PMID 40470730, 2025). "Another notable aspect of our study was the use of a reliable preclinical organoid model of EGC combined with scRNA‐seq data and the finding that IL‐33+ endothelial cells can promote angiogenesis and tumor proliferation in EGC by influencing adhesion molecules (PECAM1, CD34, and KRT17)." (PMID 40860436, 2025). "KRT17 is expressed at a high level by cells of HNSCC tumor lines and is absent in normal epithelium but is induced when it is damaged at the stage of hyperproliferation." (PMID 38540309, 2024). "Moreover, we describe KRT17 to be a candidate biomarker for HNSCC cell differentiation and early tumor detection." (PMID 39358322, 2024). "In the meantime, other confirmations have also appeared that KRT17 expression was expanded in tumor tissues but not in nontumor regions." (PMID 36248412, 2022). "Besides the differential expression of KRT5 and KRT19 between the margin and tumor center, KRT6B, KRT8, KRT10, and KRT17 were identified among the proteins differentiating the cancer from control tissue." (PMID 35512017, 2022). "To access whether KRT17 is clinicopathologically correlated with OSCC, we examined protein expression of KRT17 with tissue arrays that contained 54 normal and 91 OSCC tumor tissues by IHC staining." (PMID 35706019, 2022). "Furthermore, the relationship between KRT17 and immune function was studied by using the CIBERSORT algorithm to predict the proportions of tumor-infiltrating immune cells (TIICs)." (PMID 36139022, 2022). "Epithelial makers (KRT18, KRT19, KRT17, KRT7, and CLDN4) were also highly expressed, indicating that M2 may be derived from transdifferentiation of epithelial cells in the tumor." (PMID 35265520, 2022). "The high expression of KRT17 was significantly correlated with pathological grade, but not with tumour size, TNM stage, clinical stage, lymph node metastasis or distant metastasis." (PMID 35281081, 2022). "The absence of KRT17 delays basaloid follicular hamartoma tumor initiation and growth in mice with constitutive Hh signaling in the epidermis." (PMID 33624385, 2021). "However, if a tumor cannot be diagnosed based only on histological features, staining with positive markers, including CK17 (cytokeratin 17), CK15 (cytokeratin 15), CK5/6 (cytokeratin 5/6), and p63, should be supportive." (PMID 34064849, 2021).
tumor (continued). "Consistent with above data for tumours generated from L1low cells, we found that tumours generated from shL1 cells showed increased extracellular matrix (eosin) content, expression of CALD1 and KERATIN 17 as evidenced by IHC." (PMID 32291413, 2020). "The Kaplan-Meier analysis indicated that patients with KRT17 positive tumor have a significantly shorter survival than those with negative tumor." (PMID 31602265, 2019). "Notably, though, all overexpressed keratins, i.e. KRT5A, KRT6A, KRT7, KRT14, KRT17, were found to play a role as LUAD tumor progression determinants." (PMID 30473748, 2018). "Notably, all overexpressed keratins, i.e. KRT5A, KRT6A, KRT7, KRT14, KRT17, were found to play a role as LUAD tumor progression determinants." (PMID 30473748, 2018). "The staining of KRT17 in the peripheral areas was similar to the well-differentiated areas in three tumor samples (+3 staining) with the rest of the ten tumors showing no staining for KRT17 in the peripheral less differentiated cells." (PMID 30550540, 2018). "KRT17 also modulates the expression of the transcriptional regulator AIRE (autoimmune regulator) in diseased epithelia, which induces the expression of proinflammatory cytokines and supports tumor progression." (PMID 27512993, 2016). "The reduced expression or absence of cytokeratins 5/6 and 17 (KRT5, KRT6, KRT17) was found in both tumor tissues in comparison to terminal duct lobular units in 22 normal mammary tissues (p < 0.0001)." (PMID 17389037, 2007). "Individual real‐time fluorescence quantification showed that KRT17 gene expression levels were significantly increased in tumor tissues from 145/180 patients with EC, and COL1A1 gene expression levels were significantly increased in tumor tissues from 152/180 patients." (PMID 38979664, 2024). "Moreover, despite the large number of clinical data, there is no pan-cancer evidence of a relationship between KRT17 and various tumor types." (PMID 35646078, 2022). "Interestingly, it has been reported that KRT17 was released from intermediate filaments and translocated into the nucleus via a nuclear localization signal (NLS), thereby mediating cell cycle progression and tumor growth." (PMID 34659370, 2021). "Likewise, KRT17 and SPDEF might be used to discriminate between patients with high and low tumor-load as indicated by the measured primary tumor percentage and cfDNA VAF." (PMID 33761899, 2021). "Interestingly, in both cases the KRT17 expression pattern reflected the tumor and not the normal mucosa, highlighting the reversal of KRT17 from a basal stem cell marker to a cornification-associated differentiation-indicating protein to be an early event in HNSCC development." (PMID 39358322, 2024). "To confirm the significance of KRT17 and CRISP2 during the period of tumor progression, we further analyzed their expression among normal and cancer samples in 6 datasets with larger sample size." (PMID 33624385, 2021).
cancer (132 papers, 2006 to 2026). A tumor composed of atypical neoplastic, often pleomorphic cells that invade other tissues. "Overexpression of KRT6A and KRT17 has been linked to hyperproliferation and the progression of various cancers, prompting extensive research into the mechanisms regulating their expression." (PMID 41439999, 2025). "The spatial map of module I aligns well with the cancer regions, as well as the spatial expression of module-associated genes such as KRT17, TM4SF1, and S100A4, which have been reported as PDAC markers." (PMID 40033360, 2025). "Conversely, the mesenteric lesion had enriched expression of the keratin family genes (KRT7, KRT17) involved in cancer progression as well as metastasis signature associated gene CEACAM6." (PMID 40018643, 2025). "For many types of cancer, keratin 17 can be used as a diagnostic, prognostic, and predictive marker." (PMID 39194725, 2024). "Keratin 17 has been underscored as an emerging diagnostic, prognostic, and predictive biomarker (Yang, Zhang & Wang, 2019), based on preclinical and clinical cancer studies." (PMID 36949761, 2023). "In univariate and multivariate analyses, KRT17 protein expression status was independently associated with survival and cancer stage." (PMID 35281081, 2022). "In recent years, there have been an increasing number of reports on the relationship between KRT17 and malignant tumors, especially the functional association between tumors." (PMID 35646078, 2022). "As a type I keratin, keratin 17 (K17) is associated with several skin diseases and is present in various carcinomas." (PMID 23559854, 2013). "High levels of KRT17 are associated with poor prognosis in several human cancers." (PMID 38979664, 2024). "In the present study, we report another keratin member, KRT17, and unravel the role of KRT17 in modulating cancer stemness and chemoresistance of OSCC through association with integrin β4 and several downstream signaling molecules including FAK, Src and β-catenin in OSCC." (PMID 35706019, 2022). "In addition, we found that KRT17 expression was positively correlated with cancer-associated fibroblast infiltration in COAD, DLBC, KIRC, OV, TGCT, THCA, and THYM and negatively correlated with cancer-associated fibroblast infiltration in HNSC." (PMID 35646078, 2022). "High expression of KRT17 was associated with reduced 5-year DFS in patients with advanced cancer." (PMID 35646078, 2022). "Another cytokeratin, described as a putative heterodimer partner of KRT7, i.e., KRT17, has also been shown to be significantly lower in aggressive cancers (diffuse gastric cancer), similar to the loss of KRT7 staining that we observed in tumoral prostatic glands." (PMID 35406395, 2022). "Ectopic expression of miRNA-485-5p inhibited OSCC sphere formation and caused sensitization of cancer cells towards cisplatin and carboplatin, which could be significantly rescued by KRT17 overexpression." (PMID 35706019, 2022). "Mechanistic studies in metastatic mouse TNBC tumors with higher Krt17 demonstrates higher Wnt signaling targets, cancer stem cells (CSCs), which positively correlates to several metastasis signatures, supporting clinical data." (PMID 41888575, 2026). "Critical genes like KRT16 and KRT17 played central roles across these different analytical platforms, underscoring their significance in cancer molecular dynamics." (PMID 40725485, 2025). "Keratin 17 plays a role in the development of cancer through several key processes: (I) promoting cell growth and proliferation; (II) supporting cell survival; and (III) modulating the immune system’s response." (PMID 39194725, 2024). "Tissue-specific cytokine polarization can be induced by low expression of KRT17 in cervical cancer and it is necessary to recruit effector immune cells to vulnerable cervical epithelial cells to prevent the growth of cancer." (PMID 38434984, 2024).
cancer (continued). "One of the EV mRNA markers, KRT17, was confirmed to be expressed higher in those with cancer recurrence after TURBT until recurrence, while its expression gradually decreased over a time for those without cancer recurrence during the study period." (PMID 38514751, 2024). "The expression of miRNA-485-5p and KRT17 in PC tissue and cancer cell lines was detected by Q-PCR paired with western blot assay." (PMID 38434984, 2024). "Proteomic studies and subsequent verification revealed the overexpression of the KRT17 protein in malignant tumors, which is consistent with the results of RNA screening." (PMID 38434984, 2024). "Metastasis-related cancer cell subset EP1 was characterized by gene expression of KRT17, LAMC2, and EMP1." (PMID 38818308, 2024). "Studies have found that the silence of keratin 17 (KRT17) results in significantly reduced expression of mesenchymal DNA in cancer cells leading to decreased migratory, invasive abilities, and reversing the resistance to cisplatin." (PMID 38711989, 2024). "In those who had cancer recurrence, KRT17 expression was high already before cancer recurrence was detected by cystoscopy." (PMID 38514751, 2024). "In normal healthy epithelia, KRT17 expression is restricted to the medullary compartments of hair and skin adnexa, while expression is abnormal in many types of cancer." (PMID 36765563, 2023). "In this category, the protein marker URO17 is notable for its ability to identify Keratin 17, an oncoprotein crucial in cancer cell replication." (PMID 37762677, 2023). "A growing body of literature suggests that the expression of cytokeratin 17 (K17) correlates with inferior clinical outcomes across various cancer types." (PMID 38140561, 2023). "KRT17 is also an oncogene that is highly expressed in cancers such as oral squamous cell carcinoma, breast cancer, and cervical cancer." (PMID 37762693, 2023). "In an ICB-treated cohort of 552 patients with various cancer types, cytokeratin 17 RNA expression was predictive of patient survival." (PMID 37835599, 2023). "Specifically, we measured the level of KRT17, a marker of proliferation, invasion, and poor prognosis in cancer, as a stemness marker." (PMID 37648998, 2023). "KRT17 was revealed to be highly presented in cancer tissues and has been adopted as a clinical biomarker for various human tumors." (PMID 36428672, 2022). "In this review, we summarized the expression patterns of KRT17 in a variety of malignant tumours, the role of KRT17 in the development and prognosis of different malignant tumors and its molecular mechanisms." (PMID 35281081, 2022). "In this review, we summarise the current evidence on the role of KRT17 in malignant tumours, including those focused on its abnormal expression, biological functions, molecular mechanisms and associated clinical features." (PMID 35281081, 2022). "A growing body of evidence has shown that KRT17 is abnormally expressed in a variety of human malignant tumours, suggesting that KRT17 is an oncogene." (PMID 35281081, 2022). "We obtained the survival prognosis information of patients sorted according to KRT17 expression level (high or low) for various cancer types through the Kaplan–Meier plotter." (PMID 35646078, 2022). "This section will discuss the expression and clinical significance of KRT17 in human malignant tumours, as well as the role and regulatory mechanism of KRT17 in malignant tumours." (PMID 35281081, 2022). "Although KRT17 has been studied in many types of cancer, the expression of KRT17 in specific subtypes of BC remains to be determined." (PMID 36139022, 2022). "We determined the difference in the expression of KRT17 between various cancer types in TCGA database via the TIMER2.0 webserver." (PMID 35646078, 2022). "We first studied the expression patterns of four potential biomarkers (cytokeratin 13, cytokeratin 17, Ki-67 and laminin 5 gamma 2 chain) in an exploratory cohort containing 54 surgical specimens from confirmed oral squamous malignancies." (PMID 35524231, 2022).
cancer (continued). "A novel miRNA-485-5p/KRT17/integrin/FAK/Src/ERK/β-catenin signaling pathway is unveiled to modulate OSCC cancer stemness and drug resistance to the common first-line chemotherapeutics." (PMID 35706019, 2022). "Past studies have suggested that KRT17 mediates cancer progression through the AKT/mTOR or Wnt/β-catenin axis." (PMID 36248412, 2022). "Previous studies show that Keratin 17 (KRT17) plays an important role in the development of many malignant tumors." (PMID 34935584, 2021). "For example, KRT5, KRT14, and KRT17 overexpression are related to poor survival across different types of cancers, especially breast cancers." (PMID 33441834, 2021). "Keratin 17 (K17), a member of type I acidic epithelial keratin family, has been reported to be upregulated in many malignant tumors and to be involved in promoting the development of tumors." (PMID 33324659, 2020). "Among these factors that characterize cancer cells, we have been interested in keratin 17 (KRT17) because it is consistently and strongly induced in OSCC, and because of its unique functions." (PMID 32012175, 2020). "Expression of KRT17 occurs in complex, multilayered epithelia and it is largely retained during neoplastic transformation leading to several types of cancer derived from such epithelial cells 7-10." (PMID 31602265, 2019). "KRT17 showed the same cellular localization as the other keratins in cancer cells, indicating that KRT17 was correctly incorporated into the cytoskeleton." (PMID 27512993, 2016). "This cluster expressed genes specific to basal-like and normal-like cancer subtypes, including keratin-5, keratin-17, and GGH." (PMID 17054791, 2006). "Additionally, we also observed a positive correlation between the expression of KRT17 signature with the neutrophil signature across various cancer types." (PMID 38822440, 2024). "Although the expression of keratin 17 is generally associated with an unfavorable prognosis for cancer patients, this trend does not always hold true." (PMID 39194725, 2024). "On the other hand, for those with cancer recurrence in the LV phase (N = 38, “Rec”), KRT17 expression was significantly elevated compared to not only the best threshold for UBC detection but also the expression level in the “No Rec” throughout the study period (p < 0.0001)." (PMID 38514751, 2024). "KRT17 is also overexpressed in other cancers suggesting a more general role in tumorigenesis." (PMID 38165934, 2024). "Keratin 17 (KRT17) is a key member of keratin and is dysregulated in various types of cancer." (PMID 38288377, 2024). "KRT17 has previously been reported as a potential cancer gene, but with an uncertain role." (PMID 37669321, 2023). "Keratin 17 (KRT17) is an oncogene in several types of cancer and is used as a biomarker of CRC." (PMID 38033043, 2023). "We found that KRT17 was highly expressed in cancer tissues relative to paraneoplastic tissues." (PMID 36765563, 2023). "Knockdown of KRT17 could efficiently suppress cancer cell proliferation by inhibiting the AKT/mTOR/HIF1α pathway." (PMID 36009022, 2022). "However, the prognostic significance of KRT17 in malignant tumours needs to be confirmed by a large number of clinical case studies." (PMID 35281081, 2022). "In recent years, abnormal expression of KRT17 has been found in malignant tumours, and these abnormal expressions were the mainly high expression, and this high expression is related to the occurrence, development and prognosis of malignant tumours." (PMID 35281081, 2022). "KRT17, as a multifunctional promoter and oncogene, has appeared to play an imperative role in advancing the proliferation, metastasis, and consequent deadly results of malignant tumors." (PMID 36248412, 2022). "KRT17 is a member of the KRT protein family that has been studied in several types of cancers." (PMID 36139022, 2022).